MYC (MYC proto-oncogene, bHLH transcription factor)
Diseases named in the same sentence as MYC in open-access papers (continued):
Sharing a sentence is not in itself a finding about the gene and the disease.
breast cancer (continued). "Breast cancer patients showing elevated expression of MAP2K3 have worse survival rates, particularly triple-negative, and the kinase is proposed to be oncogenic in driving MYC in certain patients." (PMID 41152984, 2025). "In summary, these findings demonstrate that acetylation of AURKB at K215 stabilizes c-MYC and may present a key mechanism through which MOF-mediated AURKB acetylation promotes breast cancer cell proliferation." (PMID 40710353, 2025). "Notably, SF3A3 has been shown to interact with MYC in breast cancer models, where translational modulation of SF3A3 induces metabolic reprogramming and acquisition of stem-like properties, ultimately potentiating MYC-driven oncogenesis in vivo." (PMID 40424306, 2025). "This approach was grounded on our previous bioinformatic and systems biology analyses, where we demonstrated the role of the miR-17/92 cluster in mediating MYC dosage compensation using the NCI-60 panel, 1000 cell lines from the Cancer Cell Line Encyclopedia, and breast cancer tissue data from TCGA." (PMID 40940795, 2025). "First, a large cohort composed of 35 HR-altered metastatic breast cancer PDXs treated with olaparib showed that olaparib-resistant models had a substantial increase in the MYC transcriptional signature as opposed to the ones that responded to treatment." (PMID 41273720, 2025). "Breast tumor organoids derived from three independent triple negative breast cancer patients (T3N0 grade 3, T2N3 grade 3, T4N2a grade 3) were assessed for endogenous expression of circPVT1, miR-33a-5p, MYC and GLS which resulted comparable to that of the originating breast cancer tissues." (PMID 40114244, 2025). "In breast cancer cell lines, miR155 has been demonstrated to promote tumour cell growth via altered glucose metabolism, by increasing activity of the phosphoinositide 3-kinases (PI3K)-FOXO3a/c-MYC axis, and reducing glucose transport 4 (GLUT4) expression." (PMID 38615118, 2024). "The activation of lactate dehydrogenase A (LDHA) promotes the production of lactate and reduces the pH value, guiding the ubiquitination and stabilization of MYC mediated by the ubiquitinase to activate the SLUG promoter, which strengthens the characteristics of CSCs in breast cancer." (PMID 38561775, 2024). "As an oncogene, METTL3 may introduce the methyl group into the mRNA of target genes such as MYC and BCL2, promoting its translation that leads to cell differentiation and proliferation and affects apoptosis in acute myeloid leukemia and breast cancer." (PMID 38966069, 2024). "In ER+ breast cancer cell lines, CDK9 targeting has been shown to reduce the level of MYC and MYB expression and E2-independent tumor cell proliferation but little information is available of the effectiveness of CDK9 inhibition in reducing tumor growth in vivo." (PMID 37801608, 2024). "MYC amplification occurred in 4 patients: 3 patients with TNBC and 1 with luminal breast cancer." (PMID 38229073, 2024). "A synthetic plant-derived miR-159 mimic was able to inhibit breast cancer cell proliferation by targeting the transcription factor TCF7, which is an effector of the Wnt signaling pathway, thereby reducing the level of MYC protein and inhibiting the growth of breast cancer cells." (PMID 38643232, 2024).
breast cancer (continued). "Our findings also showed that breast cancer patients with TOP2A, ERBB2, and MYC amplification (amp) achieved higher pCR rates than wtTOP2A, ERBB2, and MYC (56.3% (n=1) vs 13.8% (n=1), 28.4% (n=1) vs 6.1% (n=1), and 13.7% (n=1) vs 11.2% (n=1), respectively) when treated with TA regimens." (PMID 38576013, 2024). "Research exposed that MYC combined with SLUG promoter activated the transcription, which increased the expression of OCT4 and NANOG, and enhanced the characteristics of CSCs in breast cancer." (PMID 38561775, 2024). "provided evidence that MYC and FAM84B were frequently co-amplified in breast cancer." (PMID 38997648, 2024). "Therefore, we presumed that MCL-1 and MYC work cooperatively in HGBCL, as reported in a previous study on breast cancer." (PMID 38918775, 2024). "Another study showed that breast cancer cells cultured with cytokines could activate Src, which promoted the upregulation of SOX2 and c-MYC." (PMID 36721232, 2023). "MYC (FC = 0.75; 95% CI, 0.52-0.99; P < .001) (eFigure 8A-B in Supplement 1) and NOTCH1 (FC = 0.97; 95% CI, 0.81-1.13; P < .001) (eFigure 8C-D in Supplement 1) were also upregulated in TNBC tumors compared with other breast cancer subtypes." (PMID 37796506, 2023). "The previous study in breast cancer has shown that the upregulation of MNAI is controlled by transcription factors, including MYC, which may hold true over a broad range of tumors." (PMID 37456231, 2023). "Moreover, PKM2 was found to be upregulated in tamoxifen-resistant breast cancer cells, and depletion of PKM2 reversed tamoxifen resistance of breast cancer cells through a PKM2-c-MYC-Survivin pathway." (PMID 37444501, 2023). "We designed a sgRNA (single‐guide RNA) library for a genome‐wide disruption of MYC binding sites and conducted a high‐throughput screen in four MYC‐dependent cell lines: K562 (chronic myelogenous leukemia, CML), ST486 (Burkitt lymphoma, BL), HepG2 (hepatoblastoma), and MCF7 (breast cancer)." (PMID 37519063, 2023). "MYC has been reported to promote cell proliferation in breast cancer, and HER2 overexpression could lead to MYC amplification." (PMID 37759508, 2023). "In breast cancer, PFKP expression was negatively correlated with estrogen receptor and human epidermal growth factor receptor-2 and positively correlated with transforming growth factor-β and MYC expression." (PMID 37151384, 2023). "MYC expression (probe 202431_at*) was not altered (Mann-Whitney test p-value = 0.69) in response to trastuzumab treatment in HER2-positive breast cancer patients." (PMID 37801436, 2023). "Importantly, MYC overexpression strongly reduced the efficacy of AZD8055 and everolimus, resulting in shortened mammary tumor–specific survival compared with the mTORi-treated cohort harboring MDA-MB-468 without MYC overexpression." (PMID 37642941, 2023). "In brief, this model allows us to create triple-negative mammary tumors, driven by WNT1, but optionally also containing a MYC-ERT2 construct, which expresses supraphysiological levels of the MYC-ER fusion protein and is activated by administration of tamoxifen." (PMID 37946084, 2023). "In general, MYC or proliferative states were anti-correlated with inflammatory or invasive states; however, an invasive program was highly enriched in the TNBC subtype but depleted in ER+ breast cancer along with proliferative states (EMT and CC)." (PMID 38084922, 2023). "In breast cancer cells, SETDB1 increases the expression of c-MYC to promote cell cycle progression, enhanced growth, and colony formation, and increased c-MYC positive feedback regulates the expression of SETDB1 by directly binding to Setdb1 promoter and enhances its transcription." (PMID 38057834, 2023).
breast cancer (continued). "The fusion of macrophages and breast cancer cells strengthened the activity TCF/LEF transcription factor and promoted the expression of downstream target genes (including cyclin D1 and c-MYC), leading to the promotion of tumor progression, metastasis, and EMT process." (PMID 36721232, 2023). "Furthermore, c-MYC inhibits antitumor immune responses by downregulating MICA and MICB via miR-17, resulting in reduced cell lysis in breast cancer cells." (PMID 36721232, 2023). "Targeting c-MYC opens up new possibilities for therapeutic intervention, especially with the development of nanoparticle-mediated drug delivery strategies as revealed by αvβ3 integrin-nanoparticole-mediated drug delivery of a c-MYC inhibitor in breast cancer." (PMID 38124183, 2023). "It has been reported that the MYC mRNA, protein level, and transcriptional activity can be inhibited by DNA-damaging drugs, such as topoisomerase II inhibitors, or by ionizing radiation in MCF-7 breast cancer cells." (PMID 37111592, 2023). "Finally, MYC-RIBOTAC showed a similar effect on the reduction of MYC mRNA and protein levels as well as cellular phenotype in MDA-MB-231 breast cancer cells." (PMID 37225982, 2023). "In addition, IL-6, VEGF and NF-κB promotes the expression of c-MYC via STAT3, leading to the development of breast cancer invasion and metastasis." (PMID 36721232, 2023). "KB-1980E6.3 could elevate c-MYC protein level by maintaining the mRNA stability of c-MYC and is responsible for the breast cancer stem cells (BCSCs) self-renewal and stemness maintenance." (PMID 36721232, 2023). "In different cancers, cellular turnover of c-MYC has been regulated by different USPs, with notable examples including the maintenance of c-MYC turnover by direct physical interactions of USP28 in colon carcinoma, USP36 in breast carcinoma and USP37 in lung cancer." (PMID 36985413, 2023). "Confirming our previous observation in mouse ES cells, MYC occupancy was observed at the proximal promoter of ZNF148 in both MCF7 (ER positive, luminal subtype) and MCF10A (normal-like) breast cancer cells, and this region harbored several canonical and non-canonical E-box sequences." (PMID 36207293, 2022). "First, to assess whether c-MYC directly mediates MARK4 transcription, MARK4 expression was detected in c-MYC-knockdown breast cancer cells, where its expression was significantly downregulated in MDA-MB-231 and BT549 cells." (PMID 35449131, 2022). "Based on our finding, we posit that MYC negatively regulates ZNF148 to repress biological processes involving cellular differentiation and development, fostering cancer stem-cell-like features in breast cancer cells." (PMID 36207293, 2022). "Furthermore, hMSCs from both sources also increased the expression levels of MYC, SNAI1, and TWIST, which promote the epithelial-mesenchymal transition and migration of breast cancer cells in both cell lines." (PMID 36406002, 2022). "However, expression of YTHDF2 was recently reported to be elevated in MYC-driven TNBC compared with hormone receptor-positive and human epidermal growth factor receptor 2 positive breast cancers." (PMID 35382893, 2022). "MYC may thus be a driver gene for basal/TNBC and consequently may be a target for the development of new drugs to treat this subform of breast cancer." (PMID 35908121, 2022).
breast cancer (continued). "Hence, the HER2-MYC-PP2A axis is of clinical relevance and provides potential therapeutic targeting of breast cancers with co-amplification of HER2 and MYC." (PMID 36329884, 2022). "In metabolic alterations, transcriptional factors ERRs and their coactivators PGC-1s contribute to breast cancer progression and metastasis by modulating the transcription of their targets including OXPHOS-related genes and oncogenic genes, such as ERBB2 and MYC." (PMID 35178385, 2022). "Furthermore, a direct proportional expression between MYC and ID1/3 was observed, further strengthening the existence of a MYC, ZNF148, and ID1/3 regulatory axis in controlling the stemness in breast cancer." (PMID 36207293, 2022). "Finally, in mouse tumor models of MYC-driven AML, breast cancer, and MYCN-amplified neuroblastoma, treatment with MYCMI-7 downregulates MYC/MYCN, inhibits tumor growth, and prolongs survival through apoptosis with few side effects." (PMID 36874405, 2022). "In addition, lncRNA SNHG7, a transcriptional target of MYC, positively regulated LDHA level in glycolysis in breast cancer as well." (PMID 36033372, 2022). "In addition, amplifications in MYC have been identified within primary and metastatic histologic grade III ER+HER2− breast cancer and described as transcriptional regulator with negative impact on survival." (PMID 34146382, 2022). "MYC is also overexpressed in one third of breast cancers and PIAS1 is essential for the viability of MYC-dependent breast cancer cells, with reduced proliferation of MYC-dependent MDA-MB-231 cell line observed when PIAS1 is depleted, which is not observed in MYC-independent MCF7 cells." (PMID 35887358, 2022). "Recent observations in preclinical breast cancer models suggest that FTH1 is a significant tumor suppressor by inhibiting the expression of key oncogenes, such as c-MYC, and that its increased expression signifies a favorable prognosis and response to chemotherapy." (PMID 35447901, 2022). "Indeed, an inverse correlation between MYC and ZNF148 mRNA levels in breast cancer patients was observed." (PMID 36207293, 2022). "In a nutshell, treatment with either form of Omomyc switches off MYC targets and impacts on protumorigenic and prometastatic gene sets, downregulating cell-cycle progression, EMT, and genes related to breast cancer grade, and upregulating genes involved in tumor rejection, among many others." (PMID 36860495, 2022). "Finally, another study confirmed that a MYC‐driven gene signature correlated with TNBC status, and was even a better predictor of disease outcome in breast cancer patients." (PMID 36214609, 2022). "MYC, a well-known oncogene with broad effects involved in cell cycle and tumor metabolism, has been reported as a prognostic biomarker in ESCC and some other cancers including breast cancer and lung cancer." (PMID 35615147, 2022). "Among them, MYC is a well-known estrogen-responsive proliferative gene in breast cancer, which our current study finds is not regulated by E2 in ERβ (only) cells." (PMID 35872983, 2022). "In breast cancer, 18F-FDG PET can image basal-like cancers with deregulated MYC." (PMID 34637026, 2021). "Mechanistically, combined inhibition of BRD4-RAC1 signaling pathways targeted c-MYC-G9a-FTH1 axis and revealed a novel molecular mechanism that might play important role in inhibition of breast cancer progression." (PMID 34803511, 2021). "Collectively, the recurrent appearance of MYC in these independent analyses raises the possibility that this transcription factor governs the mechanistic link between stemness and PI3K signaling strength in pluripotent stem cells and breast cancer." (PMID 34762647, 2021).
breast cancer (continued). "In addition, in breast cancer, pathways such as HER2, MYC, and FGFR1, responsible for inhibition of apoptosis and sustained proliferation of cancer cells, endure activation." (PMID 33925129, 2021). "Not as expected, there was no obvious change in LINC00467 expression in breast cancer cells with the treatment of IL-6, hypoxia induction or silence of endogenic MYC." (PMID 33996559, 2021). "In breast cancer mir-222 inhibit PTEN, and p27Kip1, activate Akt, inhibit lncRNAGS 5, and MYC." (PMID 33482868, 2021). "Since WNT and STAT3 share common downstream target genes, such as D-type cyclins and c-MYC, we conclude that activation of both pathways is not required for opioid-mediated breast cancer migration and metastasis." (PMID 33465556, 2021). "Next, we investigated protein-protein interactions between c-MYC, G9a and FTH1 to test whether these proteins form complex in breast cancer cells." (PMID 34803511, 2021). "In addition, both c‐MYC and SURVIVIN protein expression was elevated in all three breast cancer cell lines." (PMID 33462997, 2021). "The demonstration that Ppm1d-deficient mice significantly delayed the formation of ERBB2-induced mammary tumors and that Ppm1d-null embryonic mouse fibroblasts were resistant to transformation by RAS, ERBB2, and c-MYC encouraged us to establish a genetically modified mouse model overexpressing WIP1." (PMID 34771656, 2021). "The analysis of clinical outcomes in breast cancer revealed that based on the cancer subtype, co-alteration of RRM2B with MYC, or alone may significantly impact patient outcomes." (PMID 33868369, 2021). "Barh demonstrated that in silico analysis, apart from repressing HMGA2, RAS, and MYC, let-7 may also target CYP19A1, ESR1, and ESR2, thereby potentially blocking estrogen signaling in ER-positive breast cancers." (PMID 34442460, 2021). "In lung and breast cancer cells, a correlation was shown between the expression of the ZNF121 and MYC genes: during the siRNA-mediated knockdown of ZNF121, MYC expression decreased and, accordingly, when ZNF121 was overexpressed, MYC expression increased." (PMID 34440124, 2021). "Leptin activates the JAK-STAT breast cancer pathway leading to c-MYC and BCL2 expression mediated cell growth and proliferation, whereas estrogen may regulate the development of estrogen dependent breast cancers." (PMID 34225729, 2021). "In breast cancer let-7 inhibit HMGA2, MYC, JAK-STAT-3, Caspase-3, RAS, CCND2, ERα." (PMID 33482868, 2021). "Elevated MYC has also been shown to allow PIK3CAH1047R-induced murine breast cancers to become independent of continuous PIK3CAH1047R expression." (PMID 33514588, 2021). "Interestingly, in breast cancer cell lines, BMI-1 activates the WNT pathway that in turns induces c-MYC activity, therefore maintaining a positive feedback loop between BMI-1 and c-MYC." (PMID 33126754, 2020). "In short, our study indicated that PRKD3 likely promoted the proliferation of breast cancer cells by activating ERK1/c‐MYC axis, but not ERK2‐mediated pathways." (PMID 31944568, 2020). "Additionally, ectopic expression of PRKD3 in the PRKD3‐knockout breast cancer cell lines led to the increased amount of p‐ERK1(Thr202/Tyr204), p‐c‐MYC, and c‐MYC." (PMID 31944568, 2020). "Importantly, a direct correlation between c-MYC overexpression and ABCC1 upregulation has been observed in breast cancer and aberrant expression of c-MYC has been detected in a number of human malignancies including prostate epithelial neoplasia." (PMID 32718079, 2020).